POT1 (protection of telomeres 1)
Description:
Component of the telomerase ribonucleoprotein (RNP) complex that is essential for the replication of chromosome termini. Is a component of the double-stranded telomeric DNA-binding TRF1 complex which is involved in the regulation of telomere length by cis-inhibition of telomerase. Also acts as a single-stranded telomeric DNA-binding protein and thus may act as a downstream effector of the TRF1 complex and may transduce information about telomere maintenance and/or length to the telomere terminus. Component of the shelterin complex (telosome) that is involved in the regulation of telomere length and protection. Shelterin associates with arrays of double-stranded TTAGGG repeats added by telomerase and protects chromosome ends; without its protective activity, telomeres are no longer hidden from the DNA damage surveillance and chromosome ends are inappropriately processed by DNA repair pathways. Binds to two or more telomeric single-stranded 5'-TTAGGG-3' repeats (G-strand) and with high specificity to a minimal telomeric single-stranded 5'-TAGGGTTAG-3' sequence. Binds telomeric single-stranded sequences internally or at proximity of a 3'-end. Its activity is TERT dependent but it does not increase TERT activity by itself. In contrast, the ACD-POT1 heterodimer enhances telomere elongation by increasing telomerase processivity.
Synonyms: hPot1; DKFZp586D211; CMM10; CRMCC3; GLM9; PFBMFT8; TPDS3
Tractability: PROTAC: ubiquitination databases record sites on it; its protein half-life has been measured.
Target class: Other nuclear protein
Gene: Protein-coding gene on chromosome 7 (124,822,386 to 124,929,959, reverse strand). Ensembl gene ENSG00000128513.
Subcellular location: Nucleus; Chromosome, telomere
Subcellular location (Human Protein Atlas): Nucleoplasm
Pathways (Reactome):
Cell Cycle: Inhibition of DNA recombination at telomere; Packaging Of Telomere Ends; Polymerase switching on the C-strand of the telomere; Processive synthesis on the C-strand of the telomere; Removal of the Flap Intermediate from the C-strand; Telomere C-strand (Lagging Strand) Synthesis; Telomere C-strand synthesis initiation; Telomere Extension By Telomerase
DNA Repair: Cleavage of the damaged purine; Cleavage of the damaged pyrimidine; Recognition and association of DNA glycosylase with site containing an affected purine; Recognition and association of DNA glycosylase with site containing an affected pyrimidine
Cellular responses to stimuli: DNA Damage/Telomere Stress Induced Senescence
Reproduction: Meiotic synapsis
Gene Ontology:
Molecular function: 8-hydroxy-2'-deoxyguanosine DNA binding; DEAD/H-box RNA helicase binding; G-rich single-stranded DNA binding; G-rich strand telomeric DNA binding; protein binding; single-stranded telomeric DNA binding; telomerase inhibitor activity; telomeric D-loop binding; telomeric DNA binding; telomeric G-quadruplex DNA binding; DNA binding
Biological process: establishment of protein localization to telomere; negative regulation of telomere maintenance via telomerase; positive regulation of DNA strand elongation; positive regulation of telomere maintenance via telomerase; positive regulation of telomeric D-loop disassembly; regulation of double-strand break repair via nonhomologous end joining; regulation of telomere maintenance via telomerase; telomere assembly; telomere capping; telomere maintenance via telomerase; telomeric D-loop disassembly; positive regulation of telomere maintenance; telomere maintenance
Cellular component: chromosome, telomeric region; nuclear telomere cap complex; nucleoplasm; nucleus; shelterin complex
Genetic constraint (gnomAD): Loss-of-function variants: 23 observed, 37.43 expected, observed/expected ratio (o/e) 0.61, 90% interval 0.44 to 0.87. The upper end of that interval is the gene's LOEUF score, 0.87, which puts it in group 3 of 6, group 1 being the genes least tolerant of losing a copy. Missense variants: 344 observed, 435.92 expected, observed/expected ratio (o/e) 0.79, 90% interval 0.72 to 0.86. Synonymous variants: 154 observed, 159.94 expected, observed/expected ratio (o/e) 0.96, 90% interval 0.84 to 1.1.
Gene-disease validity (ClinGen):
ClinGen rates the evidence that POT1 causes each of these diseases.
tumor predisposition syndrome 3 (autosomal dominant): Definitive. Any hereditary cancer predisposition due to variation(s) in the POT1 gene, which confers a predisposition to development of various types of benign and malignant neoplasms.
Cancer hallmarks: genome instability and mutations (suppresses)
Homologues: Orthologues: chimpanzee POT1 (99% identical), macaque POT1 (94% identical), pig POT1 (89% identical), dog POT1 (89% identical), guinea pig POT1 (83% identical), rat Pot1 (77% identical), mouse Pot1a (76% identical), rat Pot1b (73% identical), mouse Pot1b (72% identical), tropical clawed frog pot1 (50% identical), zebrafish pot1 (36% identical).
Diseases named in the same sentence as POT1 in open-access papers:
POT1 is named in the same sentence as 123 diseases in open-access papers, as found by Europe PMC text mining. Sharing a sentence is not in itself a finding about the gene and the disease. The quoted sentences say what the papers report.
melanoma (82 papers, 2014 to 2025). A malignant, usually aggressive tumor composed of atypical, neoplastic melanocytes. "More recently, POT1 constitutional variants were identified in 1.75% (4/228) of familial melanoma pedigrees in a Spanish cohort." (PMID 40350252, 2025). "Among telomere regulating genes, germline pathogenic variants (PVs) in POT1 have been found at the highest frequencies in melanoma-prone families – up to 9% – though with considerable variation across different cohorts." (PMID 40851494, 2025). "Eight (10%) patients were identified that carried pathogenic mutations in known melanoma predisposition genes POT1, MITF, OCA2, SLC45A2 and TYR." (PMID 39315505, 2025). "In this article, we report the results of POT1 germline genetic testing that has been conducted in Stockholm, Sweden, as part of the routine gene panel testing for hereditary melanoma in families with melanoma and cancer susceptibility." (PMID 40851494, 2025). "This study investigated the prevalence and pathogenicity of POT1 variants in a Swedish familial melanoma cohort." (PMID 40851494, 2025). "The findings of this study contribute to the growing understanding of POT1 variants’ role in familial melanoma." (PMID 40851494, 2025). "The entire sequence analysis of POT1 in all the study subjects identified only eight variants in high-risk melanoma patients, and only one of these has been predicted as potentially pathogenic, suggesting that POT1 mutations are almost rare." (PMID 40869905, 2025). "Both variants have been described in several other cancer patients, including those with glioma, colorectal and lung cancer, and we therefore consider them likely to result in a loss of POT1, which contributes to the melanoma risk." (PMID 39315505, 2025). "Here we report a novel, likely pathogenic POT1 missense variant (p.G95V) in familial melanoma and investigate its functional impact." (PMID 39247651, 2024). "POT1 p.(I78T) is a founder disease-causing variant associated with early-onset melanoma and additional various solid malignancies with a high tumor burden." (PMID 38540414, 2024). "Germline variants in the POT1 gene have been implicated in predisposition to cancer, primarily to melanoma and chronic lymphocytic leukemia (CLL)." (PMID 38540414, 2024). "Germline mutations of CDKN2A, CDK4, TERT, and POT1 genes have been identified as high-risk factors for melanoma susceptibility, whereas MC1R (melanocortin 1 receptor) polymorphic variants are reported in 60.5–82.1% of melanoma." (PMID 38473275, 2024). "In a recent study that analysed more than 1500 cases of sarcoma probands, POT1 PV was identified in six and associated to familial melanoma pedigree in two of these." (PMID 38839987, 2024). "Frequent mutations in shelterin genes result in several cancers, including melanoma, lung adenocarcinoma, and colorectal cancer, especially POT1 mutations are prevalent." (PMID 39578854, 2024). "POT1 germline variants have been identified in a number of familial cancer syndromes most commonly melanoma, chronic lymphocytic leukaemia, and familial cardiac angiosarcoma." (PMID 39247651, 2024). "Recent studies identified POT1 germline variants in melanoma-prone families with cases of thyroid cancer, as seen in this case." (PMID 37958811, 2023). "As such, and to inform genetic counselling, there is a need to identify which genetic variants abrogate POT1 function leading to telomere dysregulation, as well as to determine their frequency in population-ascertained melanoma cases." (PMID 36539277, 2023). "Spitzoid morphology was observed in 77% (23 of 30), 75% (3 of 4), 50% (2 of 4), and 50% (1 of 2) of melanomas from individuals with germline variants in POT1, TERF2IP, ACD, and TERT, respectively." (PMID 36876055, 2023). "The median age at diagnosis for a melanoma with spitzoid morphology was 51.5 years (range: 20-77 years) for the variant carrier group (all genes including POT1) and 52 years (range: 35-77 years) for POT1 variant carriers." (PMID 36876055, 2023).
melanoma (continued). "Spitzoid morphology in familial melanoma has been associated with germline variants in POT1, a telomere maintenance gene (TMG), suggesting a link between telomere biology and spitzoid differentiation." (PMID 36876055, 2023). "We also identified spitzoid morphology in melanomas from individuals with variants in TMG other than POT1 (TERF2IP, ACD, and TERT)." (PMID 36876055, 2023). "•Spitzoid morphology is common in familial melanoma cases from individuals with POT1, TERF2IP, ACD, and TERT germline variants." (PMID 36876055, 2023). "Germline mutations in the protection of telomeres 1 (POT1) gene have been shown to be implicated in melanoma predisposition." (PMID 36077430, 2022). "Germline and somatic mutations of POT1 have been reported to underlie a series of familial cancers, including angiosarcoma, glioma, melanoma and colorectal cancer." (PMID 36387164, 2022). "Germline and somatic alterations in POT1 have been implicated in a series of familial cancers, including angiosarcoma, glioma, melanoma and colorectal cancer." (PMID 36387164, 2022). "According to one study, POT1 seems to be one of the most commonly mutated genes in hereditary melanoma, along with CDKN2A." (PMID 35465855, 2022). "Germline disruptive variants in Protection of Telomeres 1 (POT1) predispose to a wide variety of cancers, including melanoma, chronic lymphocytic leukemia (CLL), Hodgkin lymphoma, myeloproliferative neoplasms, and glioma." (PMID 35456397, 2022). "Nevertheless POT1 germline mutations have been implicated in susceptibility for melanoma, displastic nevi and FNMTC in some families; and more recently, a novel germline variant (p.Val29Leu) of POT1 gene was reported in one family affected solely by NS-FNMTC." (PMID 35295987, 2022). "From the perspective of human genetics, somatic and germline mutations in POT1 have been associated with an increased risk for various cancers, including chronic lymphocytic leukemia, Hodgkin lymphoma, colorectal, glioma, melanoma, sarcoma, and angiosarcoma." (PMID 35323213, 2022). "POT1 loss-of-function germline mutations associated with melanoma arise in the OB region of the gene." (PMID 34442055, 2021). "In line with this, individuals with mutations in the shelterin protein Pot1 have longer telomeres at birth and increased risk of developing melanomas." (PMID 34359672, 2021). "POT1 germline mutations have been identified across various cancer types, most notably in melanoma, chronic lymphocytic leukemia, angiosarcoma and glioma." (PMID 32987645, 2020). "While one germline mutation in POT1 has already been reported in a melanoma-prone family with occurrence of thyroid cancers, we report the first of such mutations in a family affected solely by NMTCs." (PMID 32492864, 2020). "A duplicity of thyroid cancer with melanoma has been identified in a patient with a newly characterized splicing POT1 mutation (thyroid cancer was present in the patient’s untested mother’s mother)." (PMID 33050356, 2020). "Somatic mutation data obtained from The Cancer Genome Atlas (TCGA) Pan-Cancer cohort through CBioPortal suggests that POT1 is mutated in approximately 4% of sporadic melanomas (n = 444)." (PMID 32987645, 2020). "POT1 germline variants are associated with cancer susceptibility in multiple familial cancer types, most notably in melanoma." (PMID 32987645, 2020). "Germline POT1 mutations have been initially described as increasing the risk of melanoma, but later studies indicate a broader cancer spectrum associated with these mutations." (PMID 33050356, 2020). "Germline deleterious mutations in POT1 have previously been associated with susceptibility to melanoma, glioma, colorectal cancer, Li-Fraumeni-like syndrome, and chronic lymphocytic leukemia." (PMID 32492864, 2020).
melanoma (continued). "Altogether, 7/11 double mutation carriers (excluded from the analysis of clinicopathological data) carried at least one mutation in high-risk melanoma (POT1/CHEK2) or syndromic (ATM/WRN, BRCA1, BRCA2 (2x), CHEK2/RAD51D, NBN) genes." (PMID 33050356, 2020). "Loss-of-function, missense mutations or other POT1 variants were observed in familial melanoma patients in the United Kingdom, the Netherlands, and Australia and in another study also in Italy, USA, and France." (PMID 31717496, 2019). "POT1 germline mutations have been described in high risk families with melanoma, colorectal cancer, glioma, and chronic lymphocytic leukemia, and in KDR in Hodgkin lymphoma families, and demonstrate that family-based NGS approaches work likewise in cancer." (PMID 30305723, 2019). "These include CHEK2 mutations in breast cancers and also in a variety of other cancers including thyroid cancer, EWSR1 in Ewing sarcoma, RET in hereditary medullary thyroid carcinoma, NRP1 in breast cancer and germline POT1 variants in malignant melanoma." (PMID 31614935, 2019). "In the present study, in which the entire POT1 gene was sequenced in cases at high risk of melanoma and in control patients, a total of 53 variants were found." (PMID 29523635, 2018). "In melanoma-dominant or melanoma-subordinate pedigrees or in individuals carrying a BAP1, CDK4, CDKN2A, MITF, or POT1 mutation, individuals should be educated on the importance of melanoma prevention and early detection." (PMID 28283772, 2017). "The reported mutations abolish the binding of POT1 (part of the shelterin complex) to telomeres, leading to fragile telomeres and increased telomere length, a reported association with melanoma predisposition." (PMID 26433962, 2016). "Our in silico studies suggest that the putative conformational changes in POT1 proteins due to the mutations described in melanoma and glioma tumours are different from those observed for POT1R117C." (PMID 26403419, 2015). "POT1 is a susceptibility gene for familial melanoma in other populations; POT1 variants were indeed found in an independent study of melanoma-prone families from the UK and Australia." (PMID 26322273, 2015). "While mutations in the Protection of Telomeres 1 (POT1) gene are well‐established as factors in the development of melanoma and lung cancer, it has been suggested that POT1 testing could be beneficial for patients with familial cancer syndromes." (PMID 41235705, 2025). "POT1 mutations are rare and contribute to a 0.5% melanoma risk burden in the general population." (PMID 39247651, 2024). "One study reported the common occurrence of spitzoid melanocytic neoplasms, characterized by large epithelioid melanocytes with abundant cytoplasm in POT1 variant carriers, where 23 of the 30 melanomas studied had a spitzoid morphology involving at least 25% of the tumor." (PMID 38540414, 2024). "Interestingly, 7 out of 11 SNPs were found in the POT1 gene, whose pathogenic mutations have already been related to melanoma, glioma, or CRC susceptibility." (PMID 36834938, 2023). "Spitzoid morphology involving at least 25% of the tumor was observed by at least 3 dermatopathologists in 77% (23 of 30), 75% (3 of 4), 50% (2 of 4), and 50% (1 of 2) of melanomas from individuals with germline variants in POT1, TERF2IP, ACD, and TERT, respectively." (PMID 36876055, 2023). "CDKN2A, along with CDK4, TERT, and POT1 genes, are high-risk genes for melanoma." (PMID 35465855, 2022). "We report the first case of splenic marginal zone lymphoma (SMZL) arising in a patient with a germline POT1 variant: a 65-year-old male with an extensive history of cancer, including melanoma and papillary thyroid carcinoma, who presented with circulating atypical lymphocytosis." (PMID 35456397, 2022). "Histological studies of some melanomas in POT1-mutated families showed a predominance of the spitzoid morphology, suggesting that telomere dysfunction may contribute to this type of differentiation." (PMID 34442055, 2021).